NAT2 (N-acetyltransferase 2)
Diseases named in the same sentence as NAT2 in open-access papers (continued):
Sharing a sentence is not in itself a finding about the gene and the disease.
breast cancer (continued). "In view of the relationship between the expression of human NAT1 and oestrogen receptor positivity in breast cancer, we wished to investigate the effects of steroidogenic compounds and xenobiotic oestrogenic compounds, including tamoxifen, on the activity of mouse Nat2." (PMID 18280460, 2008). "Additionally, a case-control study proposed that variations in the cytochrome P450 1A2-164 A/C (CYP1A2) or N-acetyltransferase 2 (NAT2) acetylator genotype may affect the relationships between consumption of red meat or meat-related mutagens and breast cancer risk." (PMID 36230700, 2022). "Nevertheless, we cannot exclude that, because of limitations in statistical power, we were unable to detect a potential weak or moderate association or interaction between SULT1A1 genotype, smoking and breast cancer, independent of NAT2 genotype." (PMID 15743503, 2005). "In the current study, we utilized rapid (F344.WKY-Nat2rapid) and slow (F344.WKY-Nat2slow) acetylator rat strains to investigate mammary cancer risk following the administration of methylnitrosourea (MNU) or 7,12-dimethylbenzanthracene (DMBA), neither of which is biotransformed by rat NAT2." (PMID 28359264, 2017). "Our findings, using mouse Nat2 to model human NAT1 function, indicate a novel aspect to the pattern of expression of mouse Nat2/human NAT1 during embryogenesis and will be important in understanding the role of the human NAT1 as a potential biomarker in breast cancer." (PMID 17896208, 2008). "A recent report demonstrated that congenic rats expressing high levels of rat N-acetyltransferase 2 (NAT2; ortholog to human NAT1) activity exhibited more mammary tumors, and this finding was independent of carcinogen metabolism." (PMID 31531019, 2019). "At present, the status of mouse Nat2, the equivalent of human NAT1, in a model of breast cancer has not been explored." (PMID 18280460, 2008).
colorectal cancer (23 papers, 2005 to 2024). A primary or metastatic malignant neoplasm that affects the colon or rectum. "The study aimed to investigate the association between red meat consumption and variants of the N-acetyltransferase 2 (NAT2) gene with colorectal cancer." (PMID 39064045, 2024). "In those groups, the association of red meat with colorectal cancer was found to be strongest among individuals with the rapid NAT2 phenotype, intermediate among those with the intermediate phenotype and non-significant among those with slow NAT2 phenotype." (PMID 34099058, 2021). "This method can now be used as a tool for haplotyping colorectal cancers and patient-matched normal samples, with the aim of identifying NAT2 heterozygous individuals losing the functional NAT2 alleles in their tumors." (PMID 33384440, 2020). "We show that N-acetyltransferase 2 (NAT2) loss of heterozygosity can be targeted in >4% of colorectal cancers with the use of a small molecule." (PMID 32944621, 2020). "For proof of concept, we select the gastrointestinal drug metabolic enzyme NAT2 at 8p22, which is frequently lost in colorectal cancers and has a common variant with 10-fold reduced activity." (PMID 32161261, 2020). "Haplotyping of NAT2 in two different colorectal cancer cohorts revealed several combinations of alleles that encode intermediate acetylator phenotypes." (PMID 33384440, 2020). "NAT2 is associated with a high risk of colorectal cancer, mainly due to its involvement in the metabolism of aromatic and heterocyclic aromatic amines in cooked red meat." (PMID 32953273, 2020). "We report on the modifying effect of NAT2 on the association of red meat intake on the risk of colorectal cancer in a genome-wide association study (GWAS) conducted in Japanese and African Americans." (PMID 26683305, 2015). "To date, a number of epidemiological studies have investigated the potential role of NAT2 polymorphisms in colorectal cancer development." (PMID 22403658, 2012). "Based on meta-analysis from 34 studies, a significant increased risk of colorectal cancer was observed for those individuals with rapid acetylator polymorphisms in NAT2 (OR 1.07, 95% CI 1.01–1.13)." (PMID 22905173, 2012). "By mining the human genome for common SNVs affecting the functional domains of enzymes, we previously identified the loss of NAT2 as a therapeutic target for colorectal cancer, specifically in cases where the remaining NAT2 allele following LOH has reduced enzymatic activity." (PMID 39368455, 2024). "Association of meat intake with colorectal cancer, stratified by NAT2 phenotypes." (PMID 26683305, 2015). "In conclusion, this large study provides substantial support for a role of NAT2 in modifying the association between intake of red meat and, particularly, processed meat and colorectal cancer risk in Japanese and African Americans, two populations at high risk for this disease." (PMID 26683305, 2015). "Contrary to the negative result of most articles, some findings suggest that NAT2 gene variants associated with more rapid acetylation activity may be related to increased risk of colorectal cancer." (PMID 22905173, 2012). "Thirdly, the sample size is still relatively small for some stratified analyses, might fail to detect small effect of NAT2 phenotypes on colorectal cancer risk in specific stratification." (PMID 22403658, 2012). "Therefore we performed a meta-analysis to get a more precise estimate of the relationship between NAT2 phenotypes and colorectal cancer risk." (PMID 22403658, 2012). "There have been an increasing number of studies with evidence suggesting that the N-acetyltransferase 1 (NAT1) and N-acetyltransferase 2 (NAT2) genotypes may be implicated in the development of colorectal cancer (CRC) and colorectal adenoma (CRA)." (PMID 22905173, 2012). "This hypothesis is partly supported by the influence of NAT2 polymorphisms in colorectal cancer risk (revised in Agundez, 2008)." (PMID 23420707, 2012).
colorectal cancer (continued). "Stratified analysis of the NAT1, NAT2 genotype on colorectal cancer and adenoma risk." (PMID 22905173, 2012). "A study with commercial herbal supplement FastOneTM showed an increase of both EROD activity and protein level of CYP1A2, and thus suggests that intake of the herbal supplement may increase the risk of colorectal cancer in humans with the rapid NAT2 phenotype." (PMID 21217855, 2009). "Thus, the genotypes of NAT1 and NAT2 coding for the rapid acetylator phenotype carry a higher risk for colorectal cancer." (PMID 16827944, 2006). "We recently identified a subset of colorectal cancer (CRC) patients who are heterozygous for a wild-type and a low activity allele (NAT2*6) but lack the wild-type allele in their tumors due to loss of heterozygosity (LOH) at 8p22." (PMID 33384440, 2020). "Cancers of the liver, lung and kidney are also prone to LOH in the NAT2 locus on chromosome 8p2223, in similar frequency to that of colorectal cancer." (PMID 33384440, 2020). "NAT2 genotypes studied in hepatocellular carcinoma and colorectal cancer have indicated the prevalence of rapid acetylator among patient population." (PMID 16083506, 2005). "Loss of NAT2, a non-essential enzyme involved in drug metabolism, in colorectal cancers emerged as an attractive target conceptually different from synthetic lethality (ENO2, PRMT5, ME3) or targeting genes essential for cell survival (POLR2A, RPA70, or PSMC2)." (PMID 32161261, 2020). "It has been abstracted that the fast acetylators are connected with colorectal cancer especially with people who consume huge amounts of well-done meat that considered a predominant source of the carcinogenic heterocyclic amines which metabolized by NAT2." (PMID 32626768, 2020). "Cafestol and kahweol may lower colorectal cancer risk by reducing bile acid synthesis and secretion, and inhibiting the activity of CYP1A2 and NAT2." (PMID 27078843, 2017). "Moreover, an enhanced association between smoking and colorectal cancer risk in subjects with the NAT2 rapid genotype was detected and supported a role for NAT2 and tobacco smoke heterocyclic amines in the etiology of colorectal cancer." (PMID 22403658, 2012). "Individuals with the NAT2 slow phenotypes were not statistically significant associated with an increased risk to colorectal cancer compared with those carrying rapid phenotypes." (PMID 22403658, 2012). "In the present study, the overall data also failed to reveal a significant association of the NAT2 variants with colorectal adenoma, in line with the meta-analyses concerning colorectal cancer." (PMID 23226745, 2012). "This meta-analysis based on 40 studies involving over 40,000 subjects indicates that lack of sufficient evidence supporting the notion of NAT2 phenotypes correlating with the risk of colorectal cancer." (PMID 22403658, 2012). "Although the findings were not all consistent, NAT2-catalyzed O-acetylation of N-hydroxy-heterocyclic amines accounted for the association between NAT2 rapid acetylation status and increased risk of colorectal cancer among people who frequently consumed well-done meat." (PMID 27223070, 2016). "This meta-analysis suggests that the NAT2 phenotypes may not be associated with colorectal cancer development." (PMID 22403658, 2012). "The previous meta-analysis didn't support the hypothesis that NAT2 alone is an important risk factor for colorectal cancer and suggests that NAT2 rapid acetylation status has no specific effect on the risk of developing colorectal cancer." (PMID 22403658, 2012). "It has been reported that rapid acetylators genotypes of NAT2 may be at increased risk of liver and colon cancer, hepatocellular carcinoma and colorectal cancer when exposed to environmental arylamines carcinogens, due to NAT2 rapid acetylator mediated O-acetylation." (PMID 16083506, 2005).
colorectal cancer (continued). "The study showed that treatment with the biologically active form of vitamin D (1,25(OH)2D3) increases NAT2 expression and that VDR binds to the NAT2 promoter in colorectal cancer cells." (PMID 39624836, 2024). "In those groups, a significant interaction was found, with the association of red meat with colorectal cancer being strongest among individuals with the rapid NAT2 phenotype, intermediate among those with the intermediate phenotype and not significant among those with the slow NAT2 phenotype." (PMID 34099058, 2021). "Similar results were reported in colorectal cancer where heterozygous and variant genotypes of both CYP1A1*2A and CYP1A1*2C conferred risk in combinations with NAT2 only among non-smokers." (PMID 22206016, 2011).
prostate carcinoma (10 papers, 1998 to 2022). A carcinoma that arises from epithelial cells of the prostate gland. "Previous studies have investigated the association between NAT2 polymorphism and the risk of prostate cancer (PCa)." (PMID 28915684, 2017). "The increased risk of prostate cancer was observed among individuals with the NAT2 slow acetylator phenotype (OR, 1.65; 95% CI, 1.04–2.61), CYP1A1 GA + GG genotype (OR, 1.27; 95% CI, 1.02–1.59), and CYP1A2 CA + AA genotype (OR, 1.43; 95% CI, 1.03–2.00)." (PMID 29165164, 2017). "Previously, NAT2 polymorphisms have been indicated to be associated with an increased susceptibility to prostate cancer and laryngeal cancer in Asian populations." (PMID 23226745, 2012). "In conclusion, this study indicates that NAT2 rapid acetylator genotype exhibit a trend of association with the risk of developing prostate cancer, and more so in case of patients who are tobacco users." (PMID 16083506, 2005). "The results observed in the present study suggest, that NAT2 genotype has a trend of association for prostate cancer risk when considered alone (OR = 1.452, 95% CI: 0.54–1.87, P = 0.136) but is statistically non-significant." (PMID 16083506, 2005). "The present study was undertaken to study the following objectives, i) To observe the frequencies of rapid and slow acetylators (NAT2) in CaP and control individuals ii) to study effect of NAT2 genotype on modifying prostate cancer risk from tobacco use." (PMID 16083506, 2005). "Mutations at the genes CYP2D6 and NAT2 were analysed by allele-specific polymerase chain reaction and restriction mapping in DNA from 94 subjects with prostate cancer and 160 male healthy control subjects." (PMID 9823980, 1998). "The gene encoding one of these enzymes (NAT2) is located in an area where frequent allelic loss occurs in prostate cancer." (PMID 9823980, 1998). "It is considered that the NAT2 slow acetylator phenotype would increase the prostate cancer risk because this phenotype would have reduced hepatic N-acetylation for detoxification of HAA carcinogens, thus increasing the chance of hepatic N-hydroxylation for activation." (PMID 29165164, 2017). "In phase II enzymes, previous studies suggested that the genetic polymorphisms in NAT1 and/or NAT2 may modify prostate cancer risk related to exposure to HAA carcinogens." (PMID 29165164, 2017). "The data suggests that the NAT2 rapid acetylator genotypes may play an important role in determining the risk of developing prostate cancer particularly in the tobacco users of north Indian population." (PMID 16083506, 2005). "Association between NAT2 acetylator genotypes with tobacco users and prostate cancer patients." (PMID 16083506, 2005). "The synergistic interaction between the rapid acetylators genotype with tobacco users obtained in our study implies that exposure to tobacco, activates heterocyclic amines that are substrates for NAT2 which may increase the risk for prostate cancer." (PMID 16083506, 2005). "Although NAT2 is expressed in prostate epithelium and the liver, our results suggest that the expression of the NAT2 phenotype in the liver has greater metabolic influence on HAA carcinogens of prostate cancer than its expression in the prostate." (PMID 29165164, 2017). "The purpose of this study was to determine the impact of HAA intake and genetic polymorphisms in NAT2, CYP1A1, and CYP1A2 on prostate cancer in Japanese men." (PMID 29165164, 2017). "The present NAT2 genotyping study based on molecular methods in discriminating the acetylator genotypes both in controls and prostate cancer patients is the first of its kind in north Indian population." (PMID 16083506, 2005). "Among four case-control studies in Japan, one study each for colorectal, stomach, and prostate cancer investigated whether NAT2 acetylation genotype and CYP1A1 and CYP1A2 genotype modify the association between dietary HAA intake and risk of cancer." (PMID 34315542, 2021).
prostate carcinoma (continued). "The purpose of our study was to determine whether there was evidence of an association between HAA intake, polymorphisms in NAT2, CYP1A1, and CYP1A2 and prostate cancer risk in Japanese men." (PMID 29165164, 2017). "In addition, we found that the NAT2 slow acetylator phenotype, the CYP1A1 GA + GG genotype, and the CYP1A2 CA + AA genotype were associated with increased prostate cancer risk." (PMID 29165164, 2017). "Our findings agree with previous studies that showed significant association of prostate cancer for NAT2 rapid acetylator genotype in American study whereas non significant association was observed in Swedish, Danish) and Spanish population." (PMID 16083506, 2005). "And we observed that NAT2 genotypes were non-significant with PSA (P = 0.090) or Gleason score (= 0.678) for risk of prostate cancer in our population." (PMID 16083506, 2005). "Frequency distribution of NAT2 genotypes in prostate cancer patients and controls." (PMID 16083506, 2005). "We posit that this finding indicates that individuals with the NAT2 slow acetylator phenotype have reduced detoxification of HAA carcinogens and increased chance of carcinogen activation, compared with other acetylator phenotypes in individuals with prostate cancer." (PMID 29165164, 2017).
colon cancer (9 papers, 2004 to 2023). "In contrast, for heterocyclic amine-related colon cancer in which N-acetylation is negligible and O-acetylation is a carcinogen-activation step, NAT2 rapid acetylator phenotype presents a higher risk." (PMID 22238607, 2012). "For cancers in which N-acetylation is negligible and O-acetylation is an activation step such as heterocyclic amine-related colon cancer, NAT2 rapid acetylator phenotype is at higher risk." (PMID 16827944, 2006). "We observed the reference allele NAT2*4 [c.481C+c.590G+c.857G] in 22.3% and 28.0% for control and colon cancer patients, respectively." (PMID 16827944, 2006). "Similar to colon cancer, the difference in allele frequencies after genotyping the same NAT2 gene variations in 67 lung cancer patients and 243 controls was not statistically significant." (PMID 16827944, 2006). "On the other hand, for heterocyclic amine-related colon cancer, NAT2 rapid acetylator phenotype confers a higher risk." (PMID 14970847, 2004). "For example, one of the strongest cases can be made for the association of polymorphisms in N-acetyltransferase 2 (NAT2) with bladder and colon cancer." (PMID 14970847, 2004). "Indeed, some studies demonstrate a positive association between NAT2 rapid acetylator phenotype and colon cancer, but results are inconsistent." (PMID 16827944, 2006). "By contrast, a meta-analysis of 20 case-control studies on NAT2 acetylation status, and an investigation into an interaction between NAT2 and heterocyclic amines derived from meat do not provide evidence for rapid acetylators to be at higher risk for developing colon cancer." (PMID 16827944, 2006). "Individuals who frequently consume red meat and exhibit rapid acetylator NAT phenotypes, carrying NAT2*4 or NAT1*10 alleles, are at a higher risk for developing colon cancer." (PMID 37738679, 2023). "Arylamine N-acetyltransferase (NAT2) was recently reported to acetylate N1-AcSpd at the N8 position in colon cancer cells, producing N1,N8-diAcSpd." (PMID 35988653, 2022). "Although NAT2 polymorphism is said to modify CRC risk in individuals exposed to heterocyclic amine carcinogens, a meta-analysis of 20 case-control studies on NAT2 acetylation status and colon cancer risk reported no consistent effect on CRC risk." (PMID 17537267, 2007). "A meta-analysis of 20 case-control studies showed, however, that NAT2 rapid acetylation status has no specific effect on the risk of colon cancer." (PMID 16827944, 2006). "We did not obtain statistically significant differences in NAT2 allele and genotype frequencies in colon cancer patients and control group." (PMID 16827944, 2006). "However, a meta-analysis with 20 publications cited that NAT2 rapid acetylation status has no specific effect on the risk of developing colon cancer." (PMID 22905173, 2012). "As there is a recent meta-analysis of NAT2 studies on colon cancer (unlike in lung cancer), we have also undertaken a systematic review of NAT2 studies on lung cancer, and we incorporated our results in a meta-analysis consisting of 16 studies, 3,865 lung cancer patients and 6,077 control subjects." (PMID 16827944, 2006).
Hepatitis (8 papers, 2013 to 2026). Inflammation of the liver. "The slow acetylator genotype of NAT2 has been proposed to be a major risk factor for anti-TB drug-induced hepatitis in Asian populations, especially in the Chinese." (PMID 23460870, 2013). "For mild presentations, characterized by a more heterogeneous hepatitis pattern, including a higher frequency of cholestatic forms, only age ≥ 55 years, and NAT2 SA status, could be implicated." (PMID 35629211, 2022). "In recent years, genetic polymorphisms of NAT2, CYP2E1 as well as GSTs have gained more focus by linking patient’s genetic susceptibility to anti-TB drug-induced hepatitis." (PMID 23460870, 2013).